KRT6A (keratin 6A)
Diseases named in the same sentence as KRT6A in open-access papers (continued):
Sharing a sentence is not in itself a finding about the gene and the disease.
oral squamous cell carcinoma (2 papers, 2021 to 2022). "p40 mediates up-regulation of keratin 6A, 14 and cancer stem cell marker CD44, which promotes abnormal differentiation of basal epithelial cells that lead to oral squamous cell carcinoma." (PMID 35741145, 2022).
transitional cell carcinoma (2 papers, 2008 to 2020). A malignant neoplasm arising from the transitional epithelium, usually affecting the urinary bladder, ureter, or renal pelvis. "Thus, unlike other keratin isoforms, keratin 6a could potentially be a marker for transformation, at least for certain cancers such as transitional cell carcinomas." (PMID 18414623, 2008).
vitiligo (2 papers, 2022 to 2024). Generalized well circumscribed patches of leukoderma that are generally distributed over symmetric body locations and is due to autoimmune destruction of melanocytes. "While some keratinocytes in the active vitiligo data set expressed stress keratins (KRT6A, KRT16), they were mainly derived from healthy and nonlesional skin." (PMID 35653192, 2022). "Again, KRT6A- and KRT16-expressing cells were found in healthy and nonlesional acute vitiligo skin, but these populations did not express CXCL9/10." (PMID 35653192, 2022).
adenoma (1 paper, 2021). A neoplasm arising from the epithelium. "The KRT6A and KRT6B gene transcripts were significantly elevated in the adenoma (one case) compared to malignant tumors." (PMID 34065672, 2021).
alopecia (1 paper, 2021). Hair loss usually from the scalp. "However, given the observed alopecia, it is somewhat surprising that transcripts for hair-follicle-specific keratins (Krt6a, Krt6b, and Krt17) were increased." (PMID 34445339, 2021).
colon cancer (1 paper, 2024). "In a human colon cancer cell line (DLD-1), KRT6A increased the proliferation, migration and invasion of the cells." (PMID 39513911, 2024).
COVID-19 (1 paper, 2025). A disease caused by infection with severe acute respiratory syndrome coronavirus 2. "We also demonstrated that the KRT14 and KRT6A expression was elevated in basal cells from patients with mild COVID-19 but not in healthy or severe COVID-19 patients, supporting the potential role of the KRT14pos basal cells in mild disease phenotype." (PMID 40980495, 2025).
cyst (1 paper, 2021). A sac-like closed membranous structure that may be empty or contain fluid or amorphous material. "Such comparison resulted in 4 upregulated (CP, CEACAM5, DMBT1, and KRT6A) and 8 downregulated (CEL, CPA1, CPB1, ALB, SERPINA4, CA2, CLU, and AMBP) DEGs secreted in cyst fluid of high-risk IPMNs." (PMID 34790815, 2021).
cystitis (1 paper, 2022). Inflammation of the urinary bladder. "Out of 3515 identified proteins, AHNAK2 and Keratin 6A (KRT6A) were chosen for IHC validation, due to having the highest ratio of means (over 58 and 29 times more abundant in high-grade cancer compared with cystitis)." (PMID 35158796, 2022).
dental caries (1 paper, 2018). The decay of a tooth, in which it becomes softened, discolored, and/or porous. "Using genetic and intraoral examination data from 573 adults and 449 children, we identified several missense polymorphisms in KRT6A, KRT6B and KRT6C that lead to a higher risk for dental caries." (PMID 29357356, 2018).
dermatofibromas (1 paper, 2008). "Keratin 6a has been found to be overexpressed in the overlying epidermis of patients with dermatofibromas, in keratinizing and nonkeratinizing squamous cell carcinomas of the cervix, and in squamous cell carcinomas of the head and neck." (PMID 18414623, 2008).
ductal carcinoma of breast (1 paper, 2022). "On the contrary, a major mutation in the KRT6A gene (KRT6A c.745T>C) has been linked to human carcinoma (including ductal carcinoma of breast and adenocarcinoma of lung and intestine) and predicted to be pathogenic in COSMIC." (PMID 35884495, 2022).
Erythema (1 paper, 2025). Redness of the skin, caused by hyperemia of the capillaries in the lower layers of the skin. "Notably, KRT6A-overexpressing mice exhibited significantly higher erythema scores and larger erythematous areas compared with controls." (PMID 40346694, 2025). "A possible explanation is that while KRT6A contributes to angiogenesis, persistent erythema in rosacea may involve additional mechanisms beyond its direct influence." (PMID 40346694, 2025). "KRT6A expression was significantly increased in rosacea lesions and positively correlated with Investigator’s Global Assessment (IGA) scores but not with Clinical Erythema Assessment (CEA) scores, indicating its involvement in inflammation." (PMID 40346694, 2025).
head and neck cancer (1 paper, 2024). A primary or metastatic malignant neoplasm affecting the head and neck. "When comparing 11 pairs of head and neck cancer tissues with normal tissues, both KRT6A and KRT6B showed a significant increase in tumor tissues." (PMID 38398015, 2024).
head and neck squamous cell carcinoma (1 paper, 2024). A squamous cell carcinoma that arises from any of the following anatomic sites: lip and oral cavity, nasal cavity, paranasal sinuses, pharynx, larynx, and salivary glands. "The aim of this study was to evaluate type II cytokeratins (KRT): KRT6A, KRT6B, and KRT6C protein concentrations in 54 tumor and margin samples of head and neck squamous cell carcinoma (HNSCC)." (PMID 39000463, 2024).
melanocytic nevus (1 paper, 2020). A neoplasm composed of melanocytes that usually appears as a dark spot on the skin. "Transcription profiles of FABP5, IVL, KRT6A, KRT15, KRT16, and TIMP2 provided clues of prognostic implications, which might help us evaluate malignant potential of nevus and underlying carcinogenesis progress from melanocytic nevus to melanoma." (PMID 32934956, 2020). "Expression profiles of FABP5, IVL, KRT6A, KRT15, KRT16, and TIMP2 provide clues of prognostic implications, which might help us evaluate malignant potential of nevus and underlying carcinogenesis progress from melanocytic nevus to melanoma." (PMID 32934956, 2020).
meningioma (1 paper, 2023). A generally slow growing tumor attached to the dura mater. "In agreement, TRAF7-deficient MEFs also had an increased expression of several investigated TRAF7 meningioma signature genes, including IL1RL1, KRT16, KRT6A, and AQP3." (PMID 36937440, 2023). "Here, TRAF7 meningiomas expressed a high number of specific DEGs, including RAPGEFL1, KRT16, KRT6A, IL1RL1, NOS1, and others." (PMID 36937440, 2023).
nevus (1 paper, 2020). Nevus (or naevus, plural nevi or naevi, from nævus, Latin for "birthmark") is the medical term for sharply circumscribed[1] and chronic lesions of the skin or mucosa. "It suggested that significantly elevated FABP5, IVL, KRT6A, KRT15, KRT16, and TIMP2 proteins expressed in the CM than in the nevus tissues." (PMID 32934956, 2020). "Further, alterations in the expression profiles of FABP5, IVL, KRT6A, KRT15, KRT16, and TIMP2 were significantly associated with worse prognosis, indicating that these hub genes may participate in the aggressive transformation from a nevus to malignant melanoma." (PMID 32934956, 2020). "Next, to validate differential expressions of six prognostic hub genes between CM tissues and nevus tissues, we performed IHC analysis and found significantly elevated FABP5, IVL, KRT6A, KRT15, KRT16, and TIMP2 protein expressions in the CM than in the nevus tissues." (PMID 32934956, 2020).
non-melanoma skin carcinoma (1 paper, 2019). "An upregulation of KRT6A gene product has been reported in non-melanoma skin cancer." (PMID 31272500, 2019).
oral cancer (1 paper, 2024). "The increased mRNA expression levels of KRT6A and KRT6B in the paired tumor tissues of our oral cancer patients also confirmed this clinical observation." (PMID 38398015, 2024).
Oral leukoplakia (1 paper, 2024). A thickened white patch on the oral mucosa that cannot be rubbed off. "PC is a rare autosomal dominant genetic skin disorder that is divided into two subtypes: PC-1 (Jadassohn–Lewandowski type) and PC-2 (Jackson–Lawler type), in which PC-1 is caused by mutations in KRT6A or KRT16 and is characterized by oral leukoplakia." (PMID 39606016, 2024).
prostate carcinoma (1 paper, 2008). A carcinoma that arises from epithelial cells of the prostate gland. "As a control, heterotransplants derived from the human prostate carcinoma cell line PC-3 did not exhibit any staining for keratin 6a." (PMID 18414623, 2008).
rosacea (1 paper, 2025). A chronic erythematous skin disorder that affects the face. "To investigate the role of KRT6A in rosacea, we designed a short hairpin RNA (shRNA) targeting KRT6A and packaged it into a recombinant adeno-associated virus serotype 9 (AAV-shKRT6A)." (PMID 40346694, 2025). "Compared with controls, KRT6A knockdown significantly alleviated the rosacea-like phenotype, as indicated by reduced erythema scores and affected areas." (PMID 40346694, 2025). "In this study, we observed an increase in KRT6A expression in rosacea and found a significant positive correlation between KRT6A and IGA, a broad indicator of overall inflammatory status, suggesting a strong association between KRT6A and skin inflammation." (PMID 40346694, 2025). "Since LL37 treatment is a well-established model for rosacea in vitro and in vivo, we examined KRT6A expression in LL37-induced rosacea-like mice." (PMID 40346694, 2025). "Immunohistochemistry (IHC) further revealed that KRT6A, normally localized to hair follicles in healthy skin, was markedly increased in the epidermis of rosacea patients." (PMID 40346694, 2025). "Given its upregulation in rosacea and in mice with barrier dysfunction, we focused on KRT6A in this study." (PMID 40346694, 2025). "Although the correlation between KRT6A and CEA (an indicator of vascular-related erythema) was not statistically significant, we observed a positive trend, suggesting a potential role for KRT6A in vascular alterations, such as vasodilation or vascular remodeling, in rosacea." (PMID 40346694, 2025). "We first analyzed KRT6A RNA levels and their clinical correlation in rosacea lesions." (PMID 40346694, 2025). "Additionally, known rosacea triggers—including capsaicin, heat stimulation, and UVB irradiation —increased KRT6A expression in HaCaT cells." (PMID 40346694, 2025). "Compared with healthy controls, KRT6A and KRT16 mRNA levels were significantly upregulated in rosacea, whereas CLDN1, CLDN16, OCLN, and KRT17 showed no significant changes, and CLDN23 was significantly downregulated." (PMID 40346694, 2025).
skin inflammation (1 paper, 2025). "To determine whether KRT6A contributes to skin inflammation, we performed intradermal injections of a lentivirus encoding KRT6A to induce its overexpression." (PMID 40346694, 2025). "In conclusion, our findings indicate that KRT6A plays a pivotal role in skin inflammation, primarily by activating the STAT3 pathway and promoting the production of downstream proinflammatory cytokines in keratinocytes." (PMID 40346694, 2025). "The specific mechanism by which KRT6A promotes skin inflammation was investigated using mass spectrometry and immunoprecipitation assays." (PMID 40346694, 2025). "We demonstrated that KRT6A upregulation in keratinocytes promotes skin inflammation through RNF41-JAK1-STAT3 axis-mediated proinflammatory signaling." (PMID 40346694, 2025). "Keratins, key components of the epidermal barrier, play a role in skin inflammation; however, studies on KRT6A remain limited." (PMID 40346694, 2025). "Our findings indicate that KRT6A expression increases following epidermal barrier disruption and contributes to exacerbated skin inflammation in disease conditions." (PMID 40346694, 2025). "Here, we investigate the role of KRT6A in skin inflammation." (PMID 40346694, 2025).
thymoma (1 paper, 2024). A neoplasm arising from the epithelial cells of the thymus. "KRT6A and KRT17, commonly used markers for the detection of thymoma, were not significantly overexpressed in the malignant cell populations; Only KRT14 was found overexpressed in the malignant mcTEC subpopulation." (PMID 39258580, 2024).
tumor (70 papers, 2008 to 2026). "KRT6B and KRT6A, members of the keratin gene family, are closely associated with clinical stage, tumor infiltration, and metastasis in patients." (PMID 40092988, 2025). "By immunofluorescence microscopy, we validated the transcriptional phenotype of MF tumor-associated keratinocytes and showed that KRT6A+S100A8+ are specifically found in the epidermis of advanced MF samples but not in HC skin." (PMID 37669110, 2023). "KRT6A, an essential cytoskeletal component in mammalian cells, mediates alterations in tumor-associated macrophage (TAMs) subtypes through different proteins and pathways in PC and is considered a new potential therapeutic target for TAMs in PC immunotherapy." (PMID 37845218, 2023). "Noteworthily, variants of KRT6A, a gene capable of mediating tumor-associate macrophage activity, were more commonly detected in MPN–SC patients." (PMID 35884495, 2022). "In patients with NSCLC, SRXN1 and KRT6A expression was associated with the tumor–node–metastasis (TNM) stage, presence of metastasis, history of smoking and daily smoking consumption." (PMID 35071014, 2021). "Interestingly, Kmt2c KO tumours show higher mRNA and protein levels of the basal cytokeratin Krt6a, which is implicated in EMT." (PMID 36933062, 2023). "KRT6A has been shown to mediate the activity of tumor-associated macrophages (TAMs) in cancers, which could possibly be involved in the link between inflammation and cancers." (PMID 35884495, 2022). "Mechanistically, KRT6A regulates adhesion, cytoskeletal remodeling, and critical signaling pathways, thereby reshaping tumor immunity and metabolism to facilitate immune evasion and metabolic dysregulation." (PMID 41648000, 2026). "We examined the expression of individually selected differentially expressed genes that were enriched in the tumours compared to normal skin, including Myc, the cSCC markers Krt6a and Krt6b28, along with Ly6a and Anxa1 ligand." (PMID 41507151, 2026). "ITGA2hi‐PTC cells were increased in PPTC samples and exhibited high expression of ITGA2, KRT6A, SOSTDC1, KRT6B, and KRT14, genes associated with tumor progression." (PMID 40985182, 2025). "Meanwhile, KRT6A plays an important role in the proliferation, migration, and infiltration of tumor cells." (PMID 38656878, 2024). "More and more studies have confirmed a close relationship between KRT6A and tumors, showing high expression in various tumor tissues." (PMID 38656878, 2024). "Previous studies have shown that KRT6A can promote tumor cell proliferation and metastasis by remodeling Cytoskeleton, promoting epithelial-mesenchymal transition (EMT) and Cell migration." (PMID 38656878, 2024). "Increased expression of keratin 6A and the involvement of keratin 16 in the development of this type of tumor have also been reported in LUAD." (PMID 39194725, 2024). "In the unpaired analysis, the KRT81, KRT6A, and KRT17 genes, which were positively associated with FSTL3 expression, exhibited notably elevated expression in tumor tissues in comparison to that in normal tissues." (PMID 38240936, 2024). "KRT6A overexpression in LUAD promotes tumor cell proliferation, epithelial-to-mesenchymal transition (EMT), and metastasis." (PMID 39194725, 2024). "Our study reported that smokers showed significantly increased concentrations of KRT6A in the tumor samples and significantly decreased concentrations of KRT6B in the margin tissue." (PMID 39000463, 2024). "In our study, the median KRT6A protein level was significantly higher in the HNSCC tumor sample than in the margin." (PMID 39000463, 2024). "Significantly higher KRT6A protein concentration was found in the tumor samples than in the margin sample (0.01976 (0.00962–0.02825) vs. 0.00933 (0.00488–0.01938)); (p = 0.0003)." (PMID 39000463, 2024). "As well as reducing KRT6A expression in tumor tissues, a significant suppressive effect of ST on CRC cell proliferation was observed in vivo." (PMID 37647260, 2023).
tumor (continued). "ImageJ software calculated the positivity rate, and the results confirmed that ANLN, RHOV, and KRT6A were all significantly upregulated in the tumor samples." (PMID 37974107, 2023). "In line with the Krt6a upregulation, the basal marker Trp63 was also upregulated, while the expression levels of the luminal keratins Krt8/18 were lower in the KO tumours." (PMID 36933062, 2023). "On the other hand, KRT6A, commonly expressed in Basal tumours, had active chromatin marks in seven out of eight Ba/Sq samples, as well as NHU, whereas most luminal samples showed no mark or quiescent/weak repression states." (PMID 36944729, 2023). "In normal and tumor cells, FAM83A and KRT6A were expressed higher in most tumor cells than in normal cells, while CYP4B1 was the opposite." (PMID 37081097, 2023). "The expression of UBE2S, HMMR and KRT6A expression in tumor tissues was substantially higher than that in adjacent non-cancerous tissues." (PMID 37199651, 2023). "In tumor cell enriched regions, SHB, VRK2, KRT6A, GRHPR, CGA, SLC6A8, and LY6D were associated with the survival of NPC patients (P < 0.05)." (PMID 36618352, 2022). "Some studies have shown that KRT6A is overexpressed in LUAD, and the overexpression of KRT6A is positively correlated with positive lymph nodes and invasive tumours." (PMID 34060213, 2021). "The molecular mechanism whereby KRT6A expression promotes tumor progression is incompletely understood." (PMID 34235156, 2021). "Tumorigenicity assays in nude mice confirmed that the siRNA-mediated downregulation of SRXN1 and KRT6A expression inhibited tumor growth in vivo." (PMID 35071014, 2021). "Meanwhile, we observed the smoking-induced upregulation of SRXN1 and KRT6A expression in 75 matched tumor–normal tissue pairs from patients with NSCLC who were enrolled in our study." (PMID 35071014, 2021). "This suppressive effect of SRXN1 or KRT6A knockdown on tumor growth was consistent with the results in vitro." (PMID 35071014, 2021). "This short tumor latency in TTA mice is similar to the latency in MMTV-tva or keratin 6a-tva mice infected by RCAS-PyMT, confirming our previous reports that RCAS-mediated delivery of PyMT is sufficient to cause malignant transformation of mammary cells." (PMID 24265712, 2013). "We used immunohistochemistry to determine the localization of keratin 6a expression in the cells of the tumor heterotransplants." (PMID 18414623, 2008). "The results of this analysis disclosed that all four tumor heterotransplant groups expressed highly elevated levels of keratin 6a mRNA, 17- to 40-fold higher than the keratin 6a mRNA expression found in the two cell lines analyzed above." (PMID 18414623, 2008). "This is supported indirectly by the finding that keratin 6a expression is focal in tumor heterotransplants and in archival patient specimens." (PMID 18414623, 2008). "Immunostaining of keratin 6a in tumor heterotransplants showed focal staining of the tumor cells that was localized to the cytoplasm." (PMID 18414623, 2008). "This analysis showed that all four tumor heterotransplant groups contained very frequent profiles of cells that were positive for the presence of keratin 6a." (PMID 18414623, 2008). "The second goal was to determine the expression of the keratin 6a gene in tumor heterotransplants derived from the As3+- and Cd2+-transformed UROtsa cells." (PMID 18414623, 2008). "Cd2+- and As3+-transformed cells grown in serum-containing growth medium, as well as the derived tumor heterotransplants, overexpressed keratin 6a mRNA and protein compared with UROtsa cells grown in serum-containing growth medium." (PMID 18414623, 2008). "Aberrant KRT6A expression promotes cell cycle progression, epithelial-mesenchymal transition, migration, and invasion, thereby driving tumor initiation and metastasis, although tumor-suppressive effects have been observed in specific contexts." (PMID 41648000, 2026).